KRAS (KRas proto-oncogene, GTPase)
Diseases named in the same sentence as KRAS in open-access papers (continued):
Sharing a sentence is not in itself a finding about the gene and the disease.
lung adenocarcinoma (continued). "The KIF5B-RET rearrangement is detected with the frequency of 1 ~ 2 % in ‘triple marker’-negative lung adenocarcinomas, i.e., EGFR, KRAS and EML4-ALK wild type." (PMID 26268359, 2015). "In conclusion, ACK1 inhibition affects cell motility and migration particularly in the context of KRAS mutant NSCLC cell lines, and is highly expressed in lung adenocarcinoma as compared to paired surrounding non-tumor tissue." (PMID 24461128, 2014). "Screening the 35% of never smokers with adenocarcinoma of the lung who will be both EGFR and KRAS wild type should, therefore, capture 92% of the ALK rearrangements contained within the never smoking adenocarcinoma population." (PMID 22374459, 2012). "Supporting our findings, mRNA levels of NOP56 significantly correlate with that of mTOR pathway genes in KRAS-mutant cancer cells and lung adenocarcinomas, and NOP56 expression is a predictive marker of sensitivity to mTOR inhibitors in KRAS-mutant but not KRAS-wild-type cancer cells." (PMID 35039048, 2022). "Two patients with lung adenocarcinoma were both EGFR negative, ALK negative and KRAS negative." (PMID 34717570, 2021). "Therefore, in our calculations we assumed that 35% of never smokers with adenocarcinoma of the lung would be both EGFR and KRAS wild type." (PMID 22374459, 2012). "Mutations of the v-Ki-ras2 Kirsten rat sarcoma viral oncogene homology gene (KRAS) gene are the most common oncogenic drivers of non-squamous non-small cell lung carcinoma (NSCLC) and occur in approximately 25–38% of non-Asian and 8–10% of Asian lung adenocarcinoma patients." (PMID 34503114, 2021). "Therefore, among the never-smoker lung adenocarcinoma cases without any known driver alterations in oncogenes such as EGFR, KRAS, ALK, etc., the estimated fraction of BCAR4 fusion could be approximately 2.2% (1/44)." (PMID 33204025, 2021).
colon carcinoma (1,079 papers, 1991 to 2026). "The 616215-338-R-J1 colon carcinoma harboring a KRAS G12S mutation was also responsive to the combination of cirtuvivint and MTRX-1133." (PMID 40470182, 2025). "While the majority of oncogenic RAS mutations are in KRAS (commonly found in pancreas, lung, and colon carcinomas), bladder urothelial carcinomas, head and neck squamous cell carcinomas, and rhabdomyosarcomas more frequently harbor HRAS mutations." (PMID 40634537, 2025). "The KRAS G12D selective inhibitor MRTX-1133 was assessed in combination with cirtuvivint in four PDMR lines harboring the KRAS G12D mutation and the 616215-338-R-J1 colon carcinoma which harbors a KRAS G12S mutation." (PMID 40470182, 2025). "MRTX1133 (MRTX), a novel inhibitor of KRASG12D (the most common KRAS mutation found in pancreatic and colon cancers) has shown promise as a therapeutic agent." (PMID 40420168, 2025). "Research has demonstrated that the presence of KRAS mutations is associated with a more aggressive form of colon cancer, characterized by increased metastatic potential and poorer clinical outcomes." (PMID 40282985, 2025). "Most frequently observed mutations in KRAS across all colon cancer samples involved G12, G13, and Q61 codons, with a combined prevalence of 29% (44/151)." (PMID 41590338, 2025). "The RASCAL I/II studies found that KRAS mutation is associated with poor prognosis in patients with colon cancer." (PMID 40142219, 2025). "One study demonstrated that rectal and distal colon tumors are more likely to harbor specific KRAS mutations compared to proximal colon cancers." (PMID 40282985, 2025). "In summary, this study demonstrated that radiomics methods based on CT images of the VP can accurately predict the KRAS gene mutation status in patients with colon cancer." (PMID 40421293, 2025). "The immunohistochemistry-based analysis of colon cancer tissues showed that elevated SMURF1 levels correlated with poor survival of patients with KRAS mutation." (PMID 39331402, 2025). "The combination of MK-5108 and trametinib showed synergistic enhancements of antitumor effect in three colon cancer cell lines harboring KRAS or BRAF mutation." (PMID 40546348, 2025). "Consistently, the analysis of the TCGA database revealed that SMURF1 is significantly upregulated in colon cancer tissues harboring KRAS mutations, and the high SMURF1 expression is positively associated with poor survival of colon cancer patients." (PMID 39331402, 2025). "The differential metastatic patterns observed in colon cancer can be attributed to the distinct biological behaviors of tumors based on their KRAS mutation status, which influences their interaction with the tumor microenvironment and the host immune response." (PMID 40282985, 2025). "Whilst some studies suggest that KRAS mutations are more common in female patients and those with right-sided colon cancer, our data contradict this, showing a higher prevalence in males." (PMID 40949797, 2025). "KRAS gene mutations in male patients with colon cancer can inhibit ferroptosis, leading to poorer five-year survival rates." (PMID 40740876, 2025). "Collectively, this study validates SMURF1 as an attractive target for colon cancer, particularly in cases harboring KRAS mutations." (PMID 39331402, 2025). "It is known that A549 is a RAS-mutated cell line.The same as in A549 dependence of the role of JNK on cisplatin concentrationwas found with another cancer cell line, colon cancer DLD-1 cellsharboring KRAS mutations, among other mutations." (PMID 38973918, 2024). "In humans, oncogenic KRAS mutations are responsible for about 30% of lung, pancreatic, and colon cancers." (PMID 38794122, 2024). "Szmida and collaborators revealed that hypermethylation of PKCB was significantly associated with KRAS mutation, which negatively regulates colon tumor progression." (PMID 38713284, 2024).
colon carcinoma (continued). "In our analysis, right-sided colon tumors had a statistically higher incidence of liver tumors with KRAS mutations (p = 0.0241) when compared against left-sided tumors and rectal tumors." (PMID 39335120, 2024). "Our molecular analysis revealed that 49% of patients had KRAS mutations, a rate comparable to left colon tumors." (PMID 39629291, 2024). "In KRAS-mutated colon cancer, a similar tumor-supporting role of ARID1A was required for MEK/ERK signaling." (PMID 38310130, 2024). "Surprisingly, the YAP1 transcriptional co-activator promotes the growth of mutant KRAS-dependent colon cancer cells upon attenuation of KRAS allele." (PMID 39595118, 2024). "In Romania, evaluating MMR/MSI status is mainly advised for oncological stages II and III, while assessing the mutational status of the KRAS gene is specifically recommended for stage IV colon cancer." (PMID 38786321, 2024). "In humans, oncogenic KRAS mutations are responsible for at least 30% of lung, pancreatic, thyroid, liver, and colon cancers." (PMID 38794122, 2024). "The remaining patients were patients with right or left colon tumors and we compared the OS, molecular mutations (KRAS, NRAS, BRAF, MSI status), and clinicopathological features of our patients with transverse colon tumors with these patients." (PMID 39629291, 2024). "In this context, it is noteworthy that KRAS‐mutated colon carcinoma cells express high levels of BCAM and efficiently form hepatic metastases in mice, which is inhibited by BCAM‐mimetic peptides blocking LAMA5–BCAM interaction." (PMID 36647260, 2023). "Compared with the wild-type colon cancer cells, the G13D mutation on KRAS determines a reduction in the responsiveness of LoVo cells to cetuximab and panitumumab, drugs that target the epidermal growth factor receptor (EGFR)." (PMID 38139304, 2023). "The KRAS mutations in colon cancers have been associated with poorer survival and increased tumor aggressiveness." (PMID 37216135, 2023). "This is important, considering that APC mutations have been shown to cooperate with BRAF and KRAS mutations for the development of colon cancer, which are also genetic alterations present in HT-29 and SW480 cells, respectively." (PMID 37259421, 2023). "The MSI-H status was associated with colon cancer and a lower mutation rate of the KRAS gene in DMMR patients." (PMID 36937571, 2023). "A lower frequency of KRAS mutations is found in left-sided colon tumors compared to right-sided colon tumors." (PMID 37628934, 2023). "The resected specimen of the colon cancer had wild-type KRAS mutation, indicating that the patient was a candidate for anti-EGFR therapy." (PMID 37872388, 2023). "The authors found that RAB3C overexpression induces dystrophin expression to promote vesicle formation and packaging for increased exocytosis, is related to drug resistance and is correlated with PIK3CA/KRAS mutation status in colon cancer." (PMID 36652260, 2023). "In 2018, 51.6% of subjects among 7599 colon cancer patients showed KRAS mutations, and overexpression of HER2 was shown in 62.5% of mutated KRAS patients (P=0.02)." (PMID 37228916, 2023). "Another example, patients with colon cancer of the microsatellite stable type with KRAS mutations have little chance of finding new therapeutic targets." (PMID 36251535, 2023).
colon carcinoma (continued). "Although the clinical significance of KRAS mutations in colon cancer is well established, the role of the same mutations in rectal cancer has not been fully elucidated." (PMID 36900260, 2023). "To validate if KRDs can represent the KRAS mutation status in colon cancer, we obtained a well-annotated single-cell RNA sequence dataset (GSE166555) from GEO database." (PMID 38097680, 2023). "Oncogene KRAS mutations were most frequently observed in GS colon cancers (71.4%) and less frequently in CIN cancers (43.4%) and in the MSI group (28.3%, χ2 test p = 0.00003)." (PMID 37998722, 2023). "CLMP was the central immune-related gene in colon cancer, associated with the inflammatory response, KRAS signaling pathway, and T-cell infiltration." (PMID 37588985, 2023). "KRAS mutation test showed KRAS wild-type colon cancer, but she refused anti-epidermal growth factor receptor therapy." (PMID 37872388, 2023). "This fact has led to an effort to target other variants of KRAS mutation, KRAS G12D, the most common colon cancer-associated K-RAS mutant." (PMID 36836752, 2023). "Exosomes derived from colon cancer cells with mutant KRAS alleles delivered their cargo to adjacent colon cancer cells, inducing the expression of mutant KRAS protein and causing tumor cell growth and tumorigenicity." (PMID 37175872, 2023). "As is known to all, KRAS mutated colon cancer acquired resistance to anti-EGFR drugs such as cetuximab due to constitutively active of KRAS protein." (PMID 38097680, 2023). "KRYSTAL-10 is an ongoing phase 3 trial currently investigating adagrasib with cetuximab versus standard fluoropyrimidine-based chemotherapy in second-line metastatic KRAS G12C-mutated colon cancer (NCT04793958)." (PMID 37569406, 2023). "While some studies have reported that KRAS mutations are more common in right-sided colon tumors, others have found them to be more frequent in left-sided tumors." (PMID 37628934, 2023). "Based on this, a prognostic model related to KRAS mutation was established to quantify individualized KRAS-related patterns in colon cancer patients, and to predict prognosis and personal response to drugs and therapies commonly used in clinical practice." (PMID 38097680, 2023). "We included 190 KRAS mutation (KRAS mt) colon cancer and 291 KRAS wildtype (KRAS wt) colon cancer tissue samples obtained from the TCGA-COAD cohort." (PMID 38097680, 2023). "Combining MEK inhibitor and anti-PD-ligand 1 (PD-L1) markedly enhances tumor response in mice with KRAS-mutated colon cancer xenografts." (PMID 37808191, 2023). "Most studies have found that the frequency of exon 2 KRAS mutations in the rectum is similar to that of left-sided colon cancers and lower than that of right-sided colon cancers." (PMID 37628934, 2023). "Although KRAS is one of the most frequently mutated genes in colon cancer, it is difficult to develop targeted drugs due to its binding to GTP and the lack of pocket structure in the active site." (PMID 36678567, 2023). "In this current study, because of this reason and their different genetical background (HT-29 cell line is BRAF-mutated colorectal adenocarcinoma; on the other hand, the HCT-116 cell line is KRAS-mutated colon carcinoma), we have selected these lines." (PMID 36547904, 2022). "Although KRAS mutation is proposed to modulate tumor immunity, its biomarker value in colon cancer immunotherapy was found to be weak." (PMID 36483562, 2022). "This is exemplified by resistance to anti-EGFR therapies in colon cancer, which can be mediated by downstream KRAS- or NRAS-activating mutations." (PMID 35625759, 2022).
colon carcinoma (continued). "For example, a study of colon cancer with KRAS gene mutation has shown that miR-10b is selectively increased in KRAS wild-type-derived exosomes, whereas miR-100 is increased in KRAS mutant-derived exosomes." (PMID 36262830, 2022). "The current results suggest a role of KRAS mutations in the etiological pathway between adiposity and colon cancer risk in women (adiposity was only associated with KRASmut colon cancers)." (PMID 35546360, 2022). "KRAS mutation is associated with worse prognosis in stage III or high-risk stage II colon cancer patients treated with adjuvant FOLFOX." (PMID 35456940, 2022). "Previous studies have shown that KRAS mutation can act as a biomarker of EGFR-targeted monoclonal antibody resistance in colon cancer patients and is associated with metastasis and poor prognosis." (PMID 35479956, 2022). "In this study, we aimed to investigate the clinical utility of extracellular vesicles and evDNA isolated from the plasma of colon cancer patients harboring KRAS G12D and G13D mutations." (PMID 36591510, 2022). "Liu reported that colon cancer features DNA hypermethylation and mutations in KRAS and can be stratified into genome stable (GS) subgroups." (PMID 36569910, 2022). "Noticeably, we found that the incidence of KRAS mutations was higher in right-sided colon cancers than that in left-sided ones." (PMID 36439454, 2022). "This study aimed to investigate the clinical utility of extracellular vesicles and evDNA isolated from the plasma of colon cancer patients harboring KRAS G12D and G13D mutations." (PMID 36591510, 2022). "MiRNA profiling was also shown to differentiate colon cancers according to KRAS mutation status, suggesting the existence of mutant KRAS-specific miRNA signatures." (PMID 36142304, 2022). "One previous study found that glucose deprivation resulted in the emergence of a selective pressure for KRAS mutation in colon cancer cells, thus, the mutated KRAS rendered cells tolerant of low glucose conditions." (PMID 35154470, 2022). "Exploring energy and fat intake of CRC patients has shown that polyunsaturated fat (PUFA) but not, total fat, nor saturated and monounsaturated fats, was associated with increased risk of colon tumors with specific KRAS mutations." (PMID 35057499, 2022). "A previous study on colon cancer showed that the concurrence of KRAS and PIK3CA mutations in cells induced the potential synergistic hyperactivation of the RAS/ERK and PI3K/AKT pathways, which result in uncontrolled cell proliferation and metastasis." (PMID 35326657, 2022). "It was reported that colon cancer is associated with two genetic events: the Wnt signaling pathway and KRAS mutation." (PMID 35409064, 2022). "Further analyses within the colon and rectum indicated that the differential associations of hPDI and CRC by KRAS mutation status was mainly for the colon cancer." (PMID 35998061, 2022). "Our results suggest a role of KRAS mutations in the etiological pathway between adiposity and colon cancer in women." (PMID 35546360, 2022). "For example, the expression of ATP2B4, a Plasma membrane Ca2+ ATPases (PMCAs) known as the major ATP-consuming pumps responsible for Ca2+ extrusion from the cells, is repressed in colon cancer with mutated or WT KRAS or BRAF." (PMID 35267511, 2022). "Further, expression of WT or mutant KRAS was also found to be associated with promoting resistance to these drugs in colon cancer cells and patients." (PMID 35286386, 2022). "We also identified the implication of the PCs in several markers of stemness and calcium regulators in colon cancer cells with KRAS or BRAF mutation." (PMID 35267511, 2022). "More effective treatment and biomarkers are needed because a large percentage of colon cancer is associated with the KRAS oncogenes." (PMID 35409064, 2022). "In our study, an assessment of cfDNA and evDNA of colon cancer patients with KRAS mutations and patients with wild-type KRAS yielded a sensitivity of 70% and 77%, respectively." (PMID 36591510, 2022).